MTOR (mechanistic target of rapamycin kinase)
Diseases named in the same sentence as MTOR in open-access papers (continued):
Sharing a sentence is not in itself a finding about the gene and the disease.
cancer (continued). "The activity of the mechanistic target of rapamycin (mTOR) is elevated in various types of human cancers, implicating a role in tumor progression." (PMID 25906254, 2015). "Although we show the net effect of LARP1 in these cancer cells is to stabilize and enrich protein expression, confirmed here at transcript level with mTOR, it is possible that LARP1 destabilizes some transcripts while stabilizing others." (PMID 25531318, 2015). "Numerous potential therapeutic options exist in rapamycin and its analogues, given mTOR’s versatility in function in many aspects of pain mediation, cancer, and post-transplant immunosuppression." (PMID 26024835, 2015). "Tremendous effect has been made to develop therapeutic reagents for a variety of cancer diseases by targeting mTOR inhibition." (PMID 25792980, 2015). "Numerous inhibitors of mTOR signaling pathways are undergoing preclinical and clinical trials for the treatment of a wide range of cancers." (PMID 26287365, 2015). "We also noted decreased HIF-1α levels and increased expression of Redd1/DDIT4, a stress-activated protein, which is down regulated in a subset of human cancers and also controls mTOR complex activity." (PMID 25867026, 2015). "Studies showed that pharmacologic and biological inhibition of AKT/mTOR signaling suppressed cancer cell migration, invasion, and metastasis." (PMID 26009991, 2015). "mTOR inhibitors can be used to treat cancer, particularly renal cell carcinoma and Kaposi sarcoma (KS) 10–12." (PMID 26108799, 2015). "Recent studies revealed that AMPK/mTOR signaling pathways are strongly connected in the regulation of cancer cell growth, proliferation, and survival." (PMID 26656173, 2015). "In relation to cancer metabolism mammalian target of Rapamycin (mTOR) is an important AMPK target with many efforts being made to target it in the clinic." (PMID 25812084, 2015). "Another example of an early phase clinical trial using a repurposing approach is our Phase I experience with the combination of mTOR inhibitor sirolimus and vorinostat in heavily pretreated patients with advanced cancer." (PMID 26244164, 2015). "The prognostic role of mTOR/p-mTOR expression has been studied extensively in other types of cancers, despite results were still controversial." (PMID 25680114, 2015). "In a recent cancer study, Grabiner and colleagues accessed publicly available sequencing data from tumor samples to uncover 33 MTOR alterations that conferred hyperactivation of the MTOR signaling pathway within cancer cells." (PMID 26542245, 2015). "On the other hand, overactivation of the phosphatidylinositol 3’kinase (PI3K), serine/threonine kinase Akt, and mammalian target of rapamycin (mTOR) pathway has been detected in a variety of human cancers, including RCC." (PMID 25784113, 2015). "Along with inhibition of mTOR signaling, there are several mechanisms proposed for anti-cancer effects of metformin including STAT3 inhibition leading to induction of apoptosis and effects on cancer-related miRNAs." (PMID 26284586, 2015). "In this context, metformin inhibits mammalian target of rapamycin (mTOR) signaling in several cancer cells." (PMID 26599019, 2015). "Aside from AMPK, adiponectin is a potent inhibitor of PI3K/AKT /mTOR that is able to reduce cancer cell growth exerted by insulin and growth factor-induced signaling." (PMID 26320190, 2015). "For example, BCAAs activate mammalian target of rapamycin (mTOR) signaling and enhance growth and proliferation of myocytes and epithelial cells, which is why BCAAs are increasingly used as a treatment for cancer cachexia." (PMID 26030804, 2015). "Dysregulation of the mTOR pathway has been well recognized to play an important role in cancer development." (PMID 26360779, 2015). "AZD8055 is a novel and potent ATP-competitive mTOR inhibitor, which blocks both mTORC1 and mTORC2 activation, effecting on cancer cell growth and survival." (PMID 26421002, 2015).
cancer (continued). "Inhibition of mTOR pharmacologically or by siRNA knockdown reduces lal-/- MDSCs abilities to stimulate cancer cell proliferation and to suppresses T cell proliferation and function." (PMID 25807535, 2015). "This phosphorylation of AMPKα appeared to be enzymatically inactive in relation to TSC2, ACC, and mTOR phosphorylation but still seemed able to promote cancer cell survival." (PMID 25798539, 2015). "By transducing both internal and external cellular signals, mTOR functions as a sensor of nutrients and energy, thus controlling protein synthesis and a broad panel of cell biological activities in both normal and cancer cells." (PMID 26329846, 2015). "Our findings, together with other previous studies, support the important role of MTOR signaling as a molecular regulator linking metabolic disorder and cancer in chronic HBV infection." (PMID 25909713, 2015). "Abnormal activation of the mammalian target of rapamycin (mTOR) signaling pathway has been observed in a variety of human cancers." (PMID 26221145, 2015). "The phosphatidylinositol 3-kinase/mammalian target of rapamycin (PI3K/mTOR) pathway is aberrantly activated in variable types of cancers, including in 30-50% of HCC cases." (PMID 25826091, 2015). "The signaling pathway defined by phosphoinositide 3-kinase (PI3K), AKT and mammalian target of rapamycin (mTOR) controls most hallmarks of cancer, including cell cycle, survival, metabolism, motility and genomic instability." (PMID 26356562, 2015). "Given the importance of MTOR in sustaining cancer cell growth, this event was proposed as an effective mechanism to target cancer cells." (PMID 26542945, 2015). "These cancers are often characterized by rampant angiogenesis that is promoted by mTOR signaling, and as such are particularly vulnerable to mTOR inhibition 29,30." (PMID 26108799, 2015). "Although mTOR inhibitors are effective in the treatment of some rare tumours, for the majority of cancers, their inability to potently target ribosome biogenesis, inhibit proliferation and cause apoptosis has limited their efficacy." (PMID 26206669, 2015). "In a transgenic mouse model, Sun has evaluated the role that mTOR plays in anal carcinogenesis, finding that mTOR knockout led to a delay in carcinoma onset, and thus suggesting this as a potential therapeutic target, too." (PMID 26498363, 2015). "Matrix metalloproteinases MMP-2/9, as essential factors to cancer invasion and metastasis, mainly rely on PI3K/AKT/mTOR in A549 and other carcinoma cells." (PMID 26061184, 2015). "This reparative reaction is characterized by tumor neovascularization accompanied by infiltration of immune cells and carcinoma-associated fibroblasts that stain for phosphorylated ribosomal protein S6 (pS6), downstream the PI3K/Akt/mTOR pathway." (PMID 26098779, 2015). "It has been recognized that the PI3K/Akt/mTOR pathway is a very promising target for the development of novel anti-cancer therapies in human cancer, including GBM." (PMID 24718026, 2014). "Recent studies have shown that numerous cancer/tumor cells depend on the mTOR signaling pathway to trigger the Warburg effect for efficient cellular proliferation." (PMID 24945378, 2014). "DGKα-PA production activates phosphodiesterase activity, that controls cAMP levels and the expression of cAMP responsive genes critical for cancer cell survival including mTOR and HIF-1." (PMID 25339152, 2014). "For example, it will be interesting to investigate the role of the PI3K/Akt/mTOR pathway that is regulated by Na+/K+-ATPase and which plays a major role in cancer cell survival." (PMID 25255962, 2014). "On the other hand, the biguanine and widely used anti-diabetic drug metformin can also inhibit the mTOR pathway and is actively investigated in cancer." (PMID 24456610, 2014). "In mouse models for T-cell leukemia (Molt-Luc2), treatment with pp242, an mTOR ATP-competitive inhibitor, enhanced DNA damage-induced apoptosis and delayed cancer development." (PMID 24992933, 2014).
cancer (continued). "Since PI3K/AKT/mTOR signaling axis controls cell proliferation and survival this pathway has achieved major importance as a target for cancer therapy." (PMID 25302298, 2014). "A variety of cell signaling events in the PI3K/Akt pathway are mediated by mTOR, and this pathway plays a central role in cell survival and proliferation in many types of cancer." (PMID 24676456, 2014). "mTOR is frequently activated in human cancers and is a commonly sought anticancer therapeutic target." (PMID 24393708, 2014). "As such further studies are required to compare cancer cachexia and caloric restriction in order to understand how protein synthesis and associated lipid homeostasis pathways through AMPK/mTOR and 4EBP1 are affected." (PMID 24667661, 2014). "The goal of our study was to identify therapies that effectively inhibited both mTOR activity and cancer cell metabolism in primary tumors in vivo." (PMID 25436981, 2014). "RAD001 has been previously shown to inhibit mTOR activity, thereby halting the proliferation of cancer cells, in vitro and in vivo." (PMID 24527093, 2014). "In this research topic, we have assembled a collection of articles describing recent key aspects of the role of the PI3K/mTOR pathway in cancer and the development of targeted therapies." (PMID 24795861, 2014). "In cancer cells, increased mTOR signaling is believed to allow survival under nutrient-restricted conditions of the tumor environment." (PMID 24886642, 2014). "But further studies are necessary to provide direct evidence for the role of O-GlcNAcylation in PI3K/Akt/mTOR pathway in cancer metabolism regulation." (PMID 25250015, 2014). "For example, metformin has recently received increased attention because of its potential antitumorigenic effects on several cancers by inactivation of mTOR and suppression of its downstream effectors." (PMID 25486251, 2014). "Constitutive activation of the PI3K pathway is among the most common events in human cancer, and the downstream kinase mTOR restricts autophagy in response to starvation." (PMID 24779010, 2014). "The PI3K/AKT/mTOR pathway is aberrantly activated in many cancers, including hematological malignancies." (PMID 25361005, 2014). "The mammalian target of rapamycin (mTOR) has attracted attention because of its involvement in a variety of diseases including cancer." (PMID 24498161, 2014). "And vice verse, growth factor receptors, Ras, Raf, MEK, PI3K and Akt, which all activate the mTOR/S6K/S6 pathway, are involved in cellular senescence and cancer." (PMID 25587030, 2014). "The binding of FKBP12 and rapamycin to mTOR (mammalian target of rapamycin) inhibits its role in regulating cell growth and cancer progression." (PMID 24405377, 2014). "Since mTOR was identified and cloned in 1994, it has been examined in a wide array of cancer types and aberrantly activated mTOR pathway plays an essential role in the growth of different types of tumors including ESCC." (PMID 24818169, 2014). "The PI3K/Akt-mTOR nexus is the central regulator of cell growth and the most upregulated pathway observed in ovarian and other cancers." (PMID 25026276, 2014). "At the same time, we focused on the mechanism of AKT phosphorylation to further investigate how CIP2A is involved in the PI3K/AKT/mTOR pathway, which is critical to cancer progression." (PMID 25109354, 2014). "mTOR, a master kinase, plays a critical role in the regulation of tumor cell aggressiveness and cancer metastasis and BAD phosphorylation is an important antiapoptotic mechanism of Akt signaling." (PMID 25243186, 2014). "Of interest, other pathways (PIK3/AKT/MTOR, RAS/RAK and ERK) activated via mutation in this cancer type are negatively regulated by active merlin." (PMID 24393766, 2014).
cancer (continued). "We, therefore, assume that a bidirectional interaction exists between the mTOR system and the epigenetic machinery in cancer cells, whereby the divergent Raptor behaviour points to differences in how both systems communicate." (PMID 24779401, 2014). "Although the efficacy of PI3K/Akt/mTOR inhibitors has been well documented in the treatment of human cancer, their advancement in cancer treatment has been limited due to toxicity which manifests following systemic delivery." (PMID 25144531, 2014). "While emerging evidence supports a central role of the mTOR pathway in cell growth and cancer progression, increased mTOR activity can also play a role mediating the depletion of the epithelial stem cell compartment." (PMID 24393708, 2014). "In this study, we investigated the role of a FASN inhibitor combined with an mTOR inhibitor in cancer cell growth." (PMID 24866893, 2014). "Constitutive activation of phosphatidylinositol 3-kinase (PI3K), Akt and mammalian target of rapamycin (mTOR) is known to confer drug resistance to many types of cancer, including MCL." (PMID 25216518, 2014). "In patients with advanced cancers, somatic mutations in FBXW7 usually occur with other simultaneous molecular aberrations, which can contribute to limited therapeutic efficacy of mTOR inhibitors." (PMID 24586741, 2014). "Akt, NF-κB and mTOR are pro-survival signaling proteins that are constitutively active in a variety of human cancers and confer survival advantage and resistance of cancer cells to various forms of anticancer therapies." (PMID 24603988, 2014). "Alterations of the mTOR signaling pathway are common in various cancers, including OS, and the mTOR signaling pathway is being actively pursued as a therapeutic target." (PMID 24765137, 2014). "Phosphatidylinositol 3-kinase/Akt/mTOR signaling pathway plays a central role in cancer cell metabolism reprograming." (PMID 25250015, 2014). "Rapamycin has brought a new dawn to cancer treatment due to its special mechanism of inhibiting cancer cell growth via inhibition of the mammalian target of rapamycin (mTOR), which is the key factor in cell proliferation regulation." (PMID 24918544, 2014). "The PI3K/Akt/mTOR pathway is very important in the development of cancers, and plays a key role in cellular functions including metabolism, survival, proliferation, adhesion, migration, and invasion." (PMID 25005526, 2014). "For example, dysregulated mTOR signaling fuels the destructive growth of cancers and it has been shown that mTOR is essential for growth and proliferation in early mouse embryos and embryonic stem cells." (PMID 25326687, 2014). "Currently, a phase I study is recruiting patients with advanced cancer for a combination trial with two arms: PD-0325901 plus PF-05212384 (an intravenous PI3K/mTOR inhibitor) and PF-05212384 plus irinotecan (clinicaltrials.gov identifier: NCT01347866)." (PMID 25408231, 2014). "Recent findings have indicated a key role of mTOR signaling in tumorigenesis and activation of the mTOR pathway has been reported in several human cancers." (PMID 25505994, 2014). "Most of the current mTOR inhibitors suppress the growth of cancer cells primarily by inducing apoptosis and cell cycle arrest, or impairing metastasis." (PMID 24626155, 2014). "The activation of AMPK inactivates mammalian target of rapamycin (mTOR), a stimulator of cancer cell growth and proliferation frequently hyper-activated by genetic alterations in cancer." (PMID 25427448, 2014). "Constitutive activation of the mTOR signaling had been reported in a few human cancers and higher mTOR expression had been observed in tumor tissues compared to corresponding normal tissues." (PMID 24816861, 2014). "It is well established that the mTOR- p70 S6K cascade is activated in many cancers and extensive effort has been placed on targeting this cascade in an attempt to inhibit cancer cell proliferation, tumorigenesis and metastasis." (PMID 24456610, 2014).
cancer (continued). "The PI3K/Akt and mTOR signaling pathways are important for cell survival and growth, and they are highly activated in cancer cells compared with normal cells." (PMID 24743574, 2014). "Inhibition of this pathway by targeting mTOR with agents such as rapamycin is effective in some cancer types." (PMID 24447333, 2014). "Mirk has the unusual property of being most active in quiescent cancer cells because of marked transcriptional downregulation by Akt/mTOR signaling and by MEK/erk signaling in cycling cells." (PMID 25061503, 2014). "PI3K/Akt and mTOR are well-known major regulatory signaling pathways that modulate cell survival in cancer cells." (PMID 24743574, 2014). "Our preliminary data showed that CIP2A regulates the phosphorylation status of mTOR, the target of rapamycin and finally affects the sensitivity of cancer cells to the treatment; however, how this process is actually executed has yet to be determined." (PMID 25109354, 2014). "Clinical trials are currently testing mTOR inhibitors as a possible cancer treatment; however, a common side effect of chemotherapy is that it stops new red blood cells being produced." (PMID 25201874, 2014). "These initial positive results are encouraging for further development of mTOR inhibitors as cancer preventive agents." (PMID 24829621, 2014). "Immunoblotting analysis revealed that mTOR activation was diminished when OA was added to the culture of cancer cells." (PMID 24626155, 2014). "Collectively, we proved evidence that OA was able to switch metabolic patterns from aerobic glycolysis to oxidative phosphorylation through affecting mTOR/c-Myc/PKM2 pathway in cancer cells." (PMID 24626155, 2014). "We have shown that fisetin, a plant derived small molecule as a potent inhibitor of PI3K/Akt/mTOR pathway in different cancers including prostate." (PMID 24770864, 2014). "Many mechanisms of action have been proposed for the anti-cancer properties of metformin, including its actions on mTOR and novel actions such as up-regulation of miR33a resulting in down regulated c-Myc expression." (PMID 24904823, 2014). "The answer is that cancer cells with highly increased metabolism rapidly exhaust and acidify the medium, thus inhibiting mTOR by starvation-like mechanism." (PMID 25585637, 2014). "Abnormal activation of IGF-1R/mTOR signaling has been frequently observed in a variety of cancers including HCC." (PMID 25026290, 2014). "The phosphatidylinositol-3-kinase (PI3K)/AKT/mammalian target of rapamycin (mTOR) signaling cascade is a key molecular target for cancer treatment." (PMID 25436776, 2014). "Aberrant expression of Akt/mTOR signaling pathway molecules has been seen in many types of cancer, such as non-small-cell lung cancer, colorectal cancer, and liver cancer." (PMID 25165983, 2014). "Metformin, an insulin sensitizer drug that is associated in several epidemiological studies with a reduction in cancer incidence, is able to reduce the degree of mTOR activation in many cancer cell lines." (PMID 25533006, 2014). "This again supports the potential utility of inhibiting the PI3K/Akt/mTOR pathway in chemoresistant cancers." (PMID 25221647, 2014). "The upstream and downstream elements of the mTOR pathway are dysregulated in different human cancers." (PMID 25505994, 2014). "We previously reported a PR rate of 35% in heavily pretreated patients with diverse cancers and somatic PI3 kinase mutations treated with PI3kinase/AKT/mTOR pathway inhibitors." (PMID 24742900, 2014). "For example, nelfinavir inhibits the PI3K/AKT/mTOR pathway, inhibits cancer cell proliferation, and induces endoplasmic reticulum stress, autophagy and apoptosis at concentrations that have been observed in HIV patients." (PMID 25327558, 2014). "mTOR signaling is emerging as a prominent mediator of cancer progression enhancing both proliferation and metastasis." (PMID 25283550, 2014).